APLN (apelin)
Diseases named in the same sentence as APLN in open-access papers (continued):
Sharing a sentence is not in itself a finding about the gene and the disease.
colon carcinoma (continued). "All these data suggest that apelin peptides increase colon cancer cell migration through stimulation of proteolytic enzyme activity." (PMID 30127323, 2018). "In summary, our studies indicate that apelin increases the migration and invasion abilities of colon cancer cells by several possible mechanisms." (PMID 30127323, 2018). "For this reason, we examined the actin polymerisation state in the cytoplasmic fraction of colon cancer cells incubated with apelin." (PMID 30127323, 2018). "Taken together, apelin increased the movement of colon cancer cells through several possible mechanisms." (PMID 30127323, 2018). "Through multi-level studies of cell culture, pathological specimens, and animal models, we identify the importance of Furin in apelin activity in colon cancer and liver metastasis and apelin-dm peptide as a potential therapeutic strategy, paving the way for further clinical exploration." (PMID 39962271, 2025). "Consequently, our focus in this study centered on unraveling the impact of apelin-dm on these critical processes within colon cancer and endothelial cells." (PMID 39962271, 2025). "The authors found that silencing the APLN gene had an effect on colon cancer cell migration." (PMID 37465677, 2023). "Expression and role of apelin/APJ signaling in colon cancer." (PMID 33912466, 2021). "Our previous study showed that apelin added to culture medium stimulates proliferation, migration and invasion of colon cancer cell lines, connected with increased ability to migratory protrusions formation, metalloproteases secretion, and cytoskeleton rearrangement." (PMID 31547096, 2019). "Therefore, the effect of apelin on invasion abilities of colon cancer cells was analysed using TranswellTM invasion assay." (PMID 30127323, 2018). "In this study, we examined the role of apelin in the motility regulation of colon cancer cells." (PMID 30127323, 2018). "Since the examined colon cancer cells are able to form blebs protrusions, we investigated whether apelin stimulation influenced their formation." (PMID 30127323, 2018). "The influence of tumour environment, including adipose tissue secreting apelin, on colon cancer development could be an interesting future research area and a promising target for the establishment of novel anti-cancer therapy." (PMID 30127323, 2018). "Furthermore, apelin peptides had a protective effect against colon cancer cell apoptosis induced by pro-apoptotic agents." (PMID 29875677, 2018). "In our study, we examined the influence of apelin peptides on colon cancer cell motility." (PMID 30127323, 2018). "Indeed, all the analyzed colon cancer cells express both apelin and the apelin receptor." (PMID 39962271, 2025). "Therefore, we checked the effect of apelin on proteolytic enzyme activity in colon cancer cells." (PMID 30127323, 2018). "The apelin/APJ system also plays significant roles in pathological conditions, acting as a potential gastric injury protectant, a marker for gastric and colon cancer, a lipid regulator for nonalcoholic fatty liver disease (NAFLD) and a mediator of fibrosis." (PMID 37505882, 2023). "Here, to determine the mechanism whereby endogenous Apelin regulates tumor growth, C57BL/6 WT and Apelin-KO mice (C57BL/6 background) were subcutaneously inoculated with murine colon carcinoma MC38 cells or Lewis lung carcinoma LLC cells." (PMID 34234274, 2021). "The exogenous apelin peptides, [Pyr1]-apelin-13,−13, and −36 activate the APJ receptor, which inhibits adenylyl cyclase activity in colon cancer cells." (PMID 29875677, 2018). "However, the mechanism of apelin’s action in colon cancer is still unknown." (PMID 30127323, 2018). "Overall, we present apelin-dm as a potent, selective, non-toxic inhibitor of the apelin receptor interaction, demonstrating efficacy in a mouse model of colon cancer and colorectal liver metastasis." (PMID 39962271, 2025).
colon carcinoma (continued). "Apelin-dm also attenuated tumor growth and angiogenesis induced by cancer cells in the CAM assay, and reduced tumor blood flow in mice with subcutaneous HCT116 colon cancer tumors and other cancer cell types (MDA-MB-231)." (PMID 39962271, 2025). "Therefore, the aim of our studies was to analyse if apelin is able to regulate the migration and invasion abilities of parental LS180 colon cancer cell line and the EB3, 3LNLN and 5W sublines, which have different migration abilities." (PMID 30127323, 2018). "Therefore, the influence of apelin peptides and ML221 on the proteolytic activity of colon cancer cells was examined using gelatine-FITC degradation assay." (PMID 30127323, 2018). "According to many studies apelin may prevent apoptosis; therefore, we examined if apelin could prevent staurosporin (STS)-induced apoptosis of colon cancer cells using Annexin V-FITC and propidium iodide assay." (PMID 30127323, 2018). "We found that in all cases, APLN expression was significantly elevated in both liver and colon tumours compared with surrounding non-tumour tissue from the same patient." (PMID 25597280, 2015). "Moreover, in obese men with colon cancer, the level of serum apelin was increased in comparison to non-obese patients." (PMID 31547096, 2019). "Interestingly, apelin peptides did not increase the proliferation of the colon cancer cells, whereas it did stimulate the phosphorylation of Akt kinase, whereas in human colon cancer cell line LS180, administration of apelin-13 stimulated proliferation via the JAG-1/Notch3 signaling pathway." (PMID 29875677, 2018). "However, no data focus on the effect of apelin on MMPs-dependent colon cancer cell migration." (PMID 30127323, 2018).
gestational diabetes (15 papers, 2014 to 2025). Carbohydrate intolerance first diagnosed during pregnancy. "According to another study, Apelin-13 activates the PI3K/Akt pathway in gestational diabetes (GDM) mice, improving glucose and lipid metabolism and reducing damage from oxidative stress and inflammatory response." (PMID 40138287, 2025). "Regarding gestational diabetes mellitus, the results are contradictory, where some studies reported an increase in apelin levels in mothers with this complication and others observed no change or even a decrease." (PMID 39457235, 2024). "Differences in the plasma levels of apelin and elabela were reported in patients with gestational diabetes mellitus." (PMID 36562292, 2023). "In diabetic mothers, exercise-induced apelin has preventive effects on gestational diabetes by reducing insulin and glucose in maternal circulation, reducing weight, reducing insulin resistance, and improving glucose tolerance in skeletal muscles." (PMID 36093083, 2022). "The available data on the significance of circulating apelin, chemerin and omentin in women with gestational diabetes mellitus (GDM) are inconsistent." (PMID 32087711, 2020). "During the colostral period, serum apelin concentration was significantly lower in subjects with gestational diabetes mellitus than healthy lactating subjects." (PMID 25541889, 2014). "Interestingly, the apelin level is lower in the breast milk of lactating women who have gestational diabetes." (PMID 37175743, 2023). "In the following, we will discuss the effects of apelin in gestational diabetes." (PMID 36093083, 2022). "Furthermore, apelin was hypothesized to be a mediator of metabolic disorders, such as gestational diabetes." (PMID 39457235, 2024). "One-way logistic regression analysis revealed a significant increase in the risk of gestational diabetes mellitus (GDM) with a rise in chemerin concentration by 10 ng, LCN2 by 1 ng, and apelin by 1 ng (1000 pg)." (PMID 38203346, 2023). "The aim of this study is to determine serum adiponectin, chemerin, lipocalin 2 and apelin levels in GDM patients, assess the correlation between these adipokines and discuss their possible role in the diagnosis and pathogenesis of gestational diabetes mellitus." (PMID 38203346, 2023). "In the second trimester, apelin levels also are reported to be higher in patients with gestational diabetes than in controls, with a negative correlation with triglycerides (TG) and total cholesterol." (PMID 36093083, 2022).
glioma (15 papers, 2014 to 2024). A benign or malignant brain and spinal cord tumor that arises from glial cells (astrocytes, oligodendrocytes, ependymal cells). "In cerebral tumors, exploration of the endothelial secretome identified the vasopeptide apelin (APLN) as a central regulator for endothelial-mediated maintenance of patient-derived glioma stem-like cells in vitro and in vivo." (PMID 34858421, 2021). "Although we cannot discount alternative sources of apelin peptides are involved in vivo, taken together the results of this study indicate that endothelial-derived apelin is an important factor for glioma growth." (PMID 29053791, 2017). "The present study has identified the vasoactive peptide apelin as a critical factor involved in glioma growth." (PMID 29053791, 2017). "Moreover, APLN inhibition seems to further reduce the proliferation of glioma stem cells and confer neuroprotection in the brain." (PMID 34359800, 2021). "In addition, in murine GL261 glioma, APLN expression became localized to newly forming tumor vessels but remained absent from GL261 tumor cells." (PMID 32545380, 2020). "Moreover, loss-of-APLN in the tumor microenvironment of APLN-KO mice showed that APLN expression controls patterning of the glioma vasculature." (PMID 32545380, 2020). "In models of glioma, targeting Apelin promoted invasiveness of tumor cells positive for APLNR." (PMID 31690961, 2020). "However, in agreement with the results from the Uribesalgo study, suppression of Apelin function combined with anti‐angiogenic therapy resulted in efficient decrease in glioma progression." (PMID 31318171, 2019). "In glioma, Apelin depletion resulted in increased tumor invasive behavior." (PMID 31318171, 2019). "In contrast, neither the APELA receptor (APLNR) nor the other ligand that binds to this receptor Apelin (APLN) was associated with patient outcome in glioma or GBM." (PMID 30917521, 2019). "However, combined targeting of VEGFR2 and Apelin improved survival of glioma bearing mice." (PMID 31690961, 2020). "These genes include HMGA1 in glioma, AKT1 in glioma, PTC, GC, and HCC, HEMGN in PTC, APLN and MMP19 in GC, WNT1 in CRC, NUPR1 in CRC and OSCC, LY6E and CTSB in CHOL, KLK4 and PLXNB2 in OC, and HDAC4 and STAT3 in SaOS." (PMID 36175921, 2022). "Additionally, studies have demonstrated that apelin/APJ promotes cell invasion and metastasis in gastric cancer, colorectal cancer and glioma." (PMID 39434201, 2024). "These miR-637-targeted genes include HMGA1, CDK6, and WNT7A in glioma, HEMGN in PTC, APLN in GC, USP21 in HCC, LY6E and CTSB in CHOL, NUPR1 in OSCC and MM, HDAC4 in SaOS, ABL1 in CML, KLK4 in OC, PLXNB2 in OC, AKT1 in TNBC, PTC, and HCC, AKT3 in TNBC, and RING1 in CCa." (PMID 36175921, 2022). "Furthermore, these upregulated miRNAs in APTE were significantly enriched in cancer, glioma, and PI3K-Akt signaling pathways, whereas the downregulated miRNAs observed in CTEPH were mainly enriched in cancer and apelin signaling pathways." (PMID 34122072, 2021).
hepatocellular carcinoma (15 papers, 2016 to 2025). A malignant tumor that arises from hepatocytes. "We found, among others, the gene encoding for apelin specifically and drastically downregulated in muscles of only Yoshida hepatoma-bearing rats." (PMID 35406586, 2022). "KEGG analysis presented that upregulated DEGs were mostly involved in hepatocellular carcinoma, Kaposi sarcoma-associated herpesvirus infection, the phosphatidylinositol signaling system, circadian entrainment, and the apelin signaling pathway." (PMID 34803519, 2021). "The result represented that upregulated DEGs were significantly associated with 5 KEGG pathways, including ‘hepatocellular carcinoma,' ‘Kaposi sarcoma-associated herpesvirus infection,' ‘phosphatidylinositol signaling system,' ‘circadian entrainment,' and ‘apelin signaling pathway'." (PMID 34803519, 2021). "Apelin was among the most downregulated genes in hepatoma-bearing rats: its expression was strikingly reduced to 8% of controls." (PMID 35406586, 2022). "We found that the mRNA levels of apelin decrease in muscles from cachectic hepatoma-bearing rats and three mouse models of cachexia." (PMID 35406586, 2022). "APLN plays carcinogenic a role in the development of hepatocellular carcinoma and is a promising drug target for the treatment of hepatocellular carcinoma." (PMID 34163524, 2021). "We identified Apelin (APLN) as an outlier gene up-regulated in hepatocellular carcinoma (HCC) through RNA-Seq and microarray analysis." (PMID 31410213, 2019). "Hepatoprotective activities of Fc-apelin against inflammation were evaluated in LPS mice and/or hepatoma Huh-7 cells with respect to serum ALT, apoptosis, oxidative stress, macrophage infiltration and gene expression." (PMID 30061611, 2018). "In hepatoma HepG2 cells, apelin promotes autophagy by inducing the phosphorylation of ERK1/2 and upregulating the expression of Beclin1." (PMID 29340118, 2017). "Furthermore, apelin induced tumor growth in murine models of mammary and hepatocellular carcinoma by promoting angiogenesis." (PMID 33707612, 2021). "Apelin overexpression was reported in muscle-invasive bladder cancer and hepatocellular carcinoma." (PMID 33707612, 2021). "The apelin/APJ system is confirmed to be a signal for arteriogenesis in hepatocellular carcinoma." (PMID 33171641, 2020). "To further determine whether Fc-apelin had anti-apoptotic effects at the cellular level, we treated human hepatoma Huh-7 cells with LPS and/or Fc-apelin and found that Fc-apelin could ameliorate LPS-induced apoptosis." (PMID 30061611, 2018). "We demonstrated that administration of Fc-apelin fusion protein attenuated the apoptosis and ROS production both in cultured hepatoma cells and in mice challenged by LPS, suggesting that the fusion protein may exert both direct and indirect protective effects against LPS-inflicted cell damage." (PMID 30061611, 2018). "The Apelin/APJ pathway induces arteriogenesis in samples of poorly-differentiated hepatocellular carcinoma (HCC)." (PMID 27733135, 2016). "In patients with hepatocellular carcinoma, APLN mRNA was markedly higher in tumors than in nontumor tissues." (PMID 36193059, 2022). "Based on these findings, a potential miR-497-mRNA or miR-1246-mRNA regulatory network can be established, namely, miR-497-ARL2/UBE2Q1/PHF19/APLN/CHEK1/CASK/SUCO/CCNE1/KIF23, or miR-1246-AUTS2/SLAIN1, which contributes to the occurrence and development of hepatocellular carcinoma." (PMID 34163524, 2021). "The apelin/APJ induces tumor arteriogenesis, and they could work as a signal for arteriogenesis in hepatocellular carcinoma." (PMID 29340118, 2017). "Additionally, data analysis from The Cancer Genome Atlas (TCGA) indicated that hepatocellular carcinoma (HCC) tissues had higher APLN expression compared to adjacent non-tumor tissues." (PMID 39744169, 2025). "In addition, apelin and APJ are overexpressed in hepatocellular carcinoma." (PMID 29340118, 2017).
metabolic syndrome (15 papers, 2011 to 2025). A cluster of metabolic risk factors for CARDIOVASCULAR DISEASES and TYPE 2 DIABETES MELLITUS. "This study aimed to explore the genetic predisposition of the apelin-APJ system to metabolic syndrome." (PMID 31217908, 2019). "Apelin serum levels have been found to be increased in diabetic patients and in patients with metabolic syndrome and have been linked with coronary atherosclerosis." (PMID 31803136, 2019). "For females, apelin-36 were higher in metabolic syndrome subjects compared with controls (p < 0.05)." (PMID 31217908, 2019). "A recent association between apelin and TNF-alpha has been reported in subjects with the metabolic syndrome." (PMID 23227256, 2012). "For example, specific apelin genotypes were associated with lower high-density lipoprotein cholesterol in Iranian women without a metabolic syndrome." (PMID 37175743, 2023). "This suggests that apelin-based therapeutics may present a novel mechanism for clinical management or treatment of metabolic syndrome." (PMID 31472173, 2019). "Taken together, the apelin-APJ system and its genetic polymorphisms have been shown to be correlated with components of metabolic syndrome (MetS), which is characterized as a constellation of metabolic disturbances." (PMID 31217908, 2019). "Our aims were to assess the efficacy of HIIT-low volume compared to continuous aerobic exercise (CAE) in treating IR in adults with metabolic syndrome (MS) and to establish whether musclin, apelin, muscle mass and muscle composition are mediators of the effect." (PMID 29482601, 2018). "However, the association between apelin-APJ system genetic polymorphisms and metabolic syndrome was nonsignificant." (PMID 31217908, 2019).
chronic kidney disease (14 papers, 2015 to 2026). Impairment of the renal function secondary to chronic kidney damage persisting for three or more months. "The increase in apelin was also associated with an increased risk of progression, and the increased risk was correlated with the presence of hyponatremia, a chronic kidney disease and obviously an advanced cancer stage." (PMID 36553076, 2022). "In chronic kidney disease, [Pyr1]apelin-13 showed additional therapeutic potential, increasing glomerular filtration rate while reducing proteinuria." (PMID 41895070, 2026). "A randomized, double-blind, placebo-controlled, crossover study evaluated the effects of [Pyr1]-apelin-13 in 24 subjects (12 patients with chronic kidney disease (CKD) and 12 matched healthy controls)." (PMID 41515992, 2025). "In the kidneys, apelin promotes augmentation of the renal blood flow and augments diuresis, and during chronic kidney diseases, it diminishes inflammation and contributes to decreased fibrosis formation." (PMID 37408184, 2023). "HPLC–MS/MS was unable to detect apelin isoforms in plasma of healthy volunteers (n = 16) and chronic kidney disease patients (n = 4)." (PMID 35546171, 2022). "The association of serum elabela (ELA) and apelin with the progression of chronic kidney disease (CKD) is unknown." (PMID 32713238, 2020). "Plasma levels of the bioactive peptide apelin also decline with age and apelin has been shown to be protective in chronic kidney disease." (PMID 31337837, 2019). "Targeting of the apelin–apelin receptor (Apj) system may serve as a useful therapeutic intervention for the management of chronic kidney disease (CKD)‐induced skeletal muscle atrophy." (PMID 36562292, 2023). "As apelin is an adipokine and could be increased with body mass 8, therefore, these effects might be present in obese chronic kidney disease too." (PMID 26103809, 2015). "Furthermore, Apelin via the TGFBR receptor can activate SMAD and reduce Epithelial-mesenchymal transition (EMT) in kidney cells preventing chronic kidney disease (CKD)." (PMID 38881758, 2024).